CHRNB2 (cholinergic receptor nicotinic beta 2 subunit)
Diseases named in the same sentence as CHRNB2 in open-access papers:
CHRNB2 is named in the same sentence as 37 diseases in open-access papers, as found by Europe PMC text mining. Sharing a sentence is not in itself a finding about the gene and the disease. The quoted sentences say what the papers report.
epilepsy (11 papers, 2011 to 2025). A brain disorder characterized by episodes of abnormally increased neuronal discharge resulting in transient episodes of sensory or motor neurological dysfunction, or psychic dysfunction. "Since mutations of the CHRNB2 gene are associated with autosomal dominant nocturnal frontal lobe epilepsy, our data suggest that CHRNB2 may be involved in mechanisms leading to an increased risk of epilepsy in FXS." (PMID 36506088, 2022). "However, due to the complexity of the cholinergic regulation, despite clear genetic association with epilepsy the role of CHRNB2 in the pathogenesis of epilepsy is still unclear." (PMID 36506088, 2022). "Both the patients also had a second pathogenic variant, in CHRNB2, a known epilepsy gene that might have contributed to the phenotype." (PMID 32274582, 2020). "Additionally, CHRNB2, a gene that is associated with human epilepsy, resulted in a p-value of 0.055." (PMID 21518446, 2011). "Many of the selected genes have been found to be associated with neurological diseases, including autism [SHANK2], chronic pain [CACNG2], epilepsy [CHRNB2], Huntington’s disease [GRIN3A], and neurodegenerative diseases [SYBU]." (PMID 32848578, 2020). "In addition to CHRNA7, several nAChR genes have been implicated in seizure disorders including CHRNA2, CHRNA4, CHRNB2." (PMID 40880366, 2025). "Analysis of differently expressed genes in cholinergic synaptic pathway showed high variation in CHRNB2 expression and a tendency toward higher expression levels in FXS NPCs without epilepsy than in control NPCs and FXS NPCs with epilepsy." (PMID 36506088, 2022).
nicotine dependence (9 papers, 2004 to 2024). Physical and psychological dependence on nicotine. "In male Japanese subjects, the CHRNB2 polymorphism (rs4845652) may confer protection against nicotine dependence, whereas a combination of this polymorphism with the CHRNA4 risk polymorphism (rs1044397) leads to higher nicotine dependence scores." (PMID 25642160, 2014). "However, we describe human genetic evidence supporting the hypothesis that loss of CHRNB2 protects against nicotine addiction." (PMID 37308787, 2023). "Our genetic discovery will inspire future drug designs targeting CHRNB2 in the brain for the treatment of nicotine addiction." (PMID 37308787, 2023). "One receptor gene, CHRNB2 (cholinergic receptor, nicotinic, beta polypeptide 2, located on chromosome 1q21) is a functional candidate gene for nicotine dependence, since it seems to be essential for a number of reinforcing effects of nicotine in mice." (PMID 19570274, 2004). "CHRNB2 was implicated in the nicotine dependence trait, but not at genome-wide significance." (PMID 30016313, 2018).
autosomal dominant nocturnal frontal lobe epilepsy (7 papers, 2015 to 2022). A seizure disorder characterized by intermittent dystonia and/or choreoathetoid movements that occur during sleep. "Previous studies had found that Chrnb2 gene mutations induce autosomal dominant nocturnal frontal lobe epilepsy." (PMID 34957168, 2021). "The molecular nature and functional properties of acr-2(gf) show similarities to gain of function mutations in human CHRNB2, the β2 subunit of neuronal nicotinic receptors, which have been identified as causal in autosomal dominant nocturnal frontal lobe epilepsy." (PMID 27782882, 2016). "Fast ionotropic nicotinic acetylcholine receptor (nAChR) subunit genes, α2 (Chrna2), α4 (Chrna4) and β2 (Chrnb2), have been affiliated with autosomal dominant nocturnal frontal lobe epilepsy (ADNFLE) when mutated." (PMID 28825447, 2017). "Autosomal dominant nocturnal frontal lobe epilepsy (ADNFLE) is caused by mutations in the CHRNA4, CHRNA2, CHRNB2, or KCNT1(Slack) genes." (PMID 25784856, 2015).
gastric cancer (3 papers, 2021 to 2025). A primary or metastatic malignant neoplasm involving the stomach. "Our research group has previously succeeded in generating an anti-CHRNB2 mAb, which has shown growth-inhibitory effects on gastric cancer cell lines following intraperitoneal administration." (PMID 40805184, 2025). "Our group previously conducted a comprehensive gene expression analysis of biological samples from patients with metastatic gastric cancer and identified aberrantly high expression of the cholinergic receptor nicotinic beta 2 subunit (CHRNB2) in cases with distant metastases." (PMID 40805184, 2025). "In gastric cancer, CHRNB2 could promote cancer progression by PI3K-AKT and JAK-STAT pathways with unclear mechanism." (PMID 36344976, 2022).
lymph node metastasis (2 papers, 2022 to 2025). "Considering the invasive ability of pancreatic cancer cells was significant in lymph node metastasis, the relationship between CHRNB2 and migration was explored." (PMID 36344976, 2022). "CHRNB2 negatively relates to lymph node metastasis in pancreatic cancer patients." (PMID 36344976, 2022). "Hence, further study is required to substantiate the correlation between CHRNB2 and lymph node metastasis in pancreatic cancer." (PMID 36344976, 2022).
colon cancer (1 paper, 2025). "In this experiment, the growth-inhibitory effect of CHRNB2 mAb on colon cancer cell lines was demonstrated." (PMID 40805184, 2025). "Therefore, CHRNB2 may be a useful option for colon cancer peritoneal metastasis treatment in the future." (PMID 40805184, 2025).
colorectal cancer (1 paper, 2025). A primary or metastatic malignant neoplasm that affects the colon or rectum. "Clinical analysis of colorectal cancer specimens revealed a significant correlation between high CHRNB2 expression and increased risk of peritoneal recurrence, indicating its involvement in metastatic progression." (PMID 40805184, 2025). "Knockdown of CHRNB2 in colorectal cancer cell lines significantly suppressed cell proliferation, migration, and invasion and notably reduced the ability to form peritoneal metastases." (PMID 40805184, 2025). "Based on these findings, it is suggested that CHRNB2 may regulate the malignant phenotype of colorectal cancer by modulating downstream signaling cascades, including the PI3K–AKT–mTOR and β-catenin pathways." (PMID 40805184, 2025).
dementia (1 paper, 2022). Loss of intellectual abilities interfering with an individual's social and occupational functions. "Another class encountered in trials was represented by dementia therapeutic agents acting on neuronal acetylcholine receptor subunit alpha-4, neuronal acetylcholine receptor subunit beta-2, neuronal acetylcholine receptor subunit alpha-7 (gene names: CHRNA4, CHRNB2, CHRNA7, respectively)." (PMID 36467081, 2022).
injury (1 paper, 2022). Damage inflicted on the body as the direct or indirect result of an external force, with or without disruption of structural continuity. "Recently, Chrnb2 has been found to be downregulated in chronic traumatic encephalopathy stage III compared to stage II, suggesting cholinergic-related deficits post-traumatic brain injury in humans." (PMID 36436561, 2022).
Lynch syndrome (1 paper, 2025). An autosomal dominant hereditary neoplastic syndrome characterized by the development of colorectal carcinoma and a high risk of developing endometrial carcinoma, gastric carcinoma, ovarian carcinoma, renal pelvis carcinoma, and small intestinal carcinoma. "Of note, one of the MMRd associated indel mutations that we identified (within the Igf2r gene) and predicted candidate neoantigens were found in one of our Lynch CRC patient, and one other (Chrnb2) and associated candidate neoantigens were also found in a murine model of Lynch syndrome." (PMID 41256707, 2025).
nemaline myopathy (1 paper, 2012). Nemaline myopathy (NM) encompasses a large spectrum of myopathies characterized by hypotonia, weakness and depressed or absent deep tendon reflexes, with pathologic evidence of nemaline bodies (rods) on muscle biopsy. "For example, mutations in CHRNB2 are associated with nocturnal frontal lobe epilepsy and TPM3 mutations are associated with nemaline myopathy." (PMID 21821125, 2012).
Obesity (1 paper, 2021). Accumulation of substantial excess body fat. "The results revealed that 18 of the DMR genes were associated with addiction and obesity (ADCY3; ADCY9; ATF4; CDK5R1; CHRNB2; GABRD; GABRG3; GNB1; GNB3; GRK5; HDAC4; HDAC9; MAP2K1; PDE11A; PDE2A; PDE3A; PPP1CA; SLC6A3)." (PMID 34389046, 2021).
pancreatic cancer (1 paper, 2022). "The expression of CHRNB2 was further compared between tumor and paired normal tissue in 6 pancreatic cancer patients." (PMID 36344976, 2022). "Considering the key role of CHRNB2 in LNR and survival, gene set enrichment analysis (GSEA) was applied to find pathways related to CHRNB2 expression in pancreatic cancer." (PMID 36344976, 2022). "The contribution of CHRNB2 to migrative and invasive ability of pancreatic cancer cells was confirmed by Transwell assays." (PMID 36344976, 2022). "We therefore explored the function of CHRNB2 in pancreatic cancer and its role in Wnt/β-catenin pathway." (PMID 36344976, 2022). "Thus, the role of CHRNB2 in the lymph node metastasis of pancreatic cancer was further investigated." (PMID 36344976, 2022). "In conclusion, after bioinformational analysis and experimental verifications, we found that CHRNB2 could inhibit the migration and invasion of pancreatic cancer cells via limiting β-catenin pathway." (PMID 36344976, 2022). "Second, although the functions of CHRNB2 were confirmed in pancreatic cancer cells in vitro, animal experiments should also be performed which could further certify the role of CHRNB2 in vivo." (PMID 36344976, 2022). "Next, knockdown of CHRNB2 expression could acetylcholine (ACh)-independently increase the migration and invasion of pancreatic cancer cells, while CHRNB2 overexpression ACh-independently decrease the migration and invasion of pancreatic cancer cells." (PMID 36344976, 2022). "For example, the mRNA of CHRNB2 could be loaded into engineered exosomes, which may increase the protein level of CHRNB2 in pancreatic cancer cells and prevent or alleviate metastasis." (PMID 36344976, 2022). "The results suggested that CHRNB2 could significantly prevent pancreatic cancer cells from entering S stage." (PMID 36344976, 2022). "We detected the cell cycle alteration of pancreatic cancer cells after overexpressing CHRNB2." (PMID 36344976, 2022). "In general, CHRNB2 might interfere β-catenin pathway and thus decreased the expression of downstream proteins of β-catenin, which further attenuated the migration and invasion ability of pancreatic cancer." (PMID 36344976, 2022). "Moreover, pancreatic cancer tissue expresses lower CHRNB2 than normal pancreas as well." (PMID 36344976, 2022). "Therefore, we supposed that ACh could promote the potassium channel activity of nicotinic acetylcholine receptor through binding with CHRNB2 and control pancreatic cancer metastasis." (PMID 36344976, 2022). "Therefore, CHRNB2 was considered to inhibit the EMT process in pancreatic cancer cells." (PMID 36344976, 2022). "We evaluated the relationship between CHRNB2 and Epithelial-to-mesenchymal transition (EMT) process, which is considered to foster the metastasis of malignant tumors, including pancreatic cancer." (PMID 36344976, 2022). "Meanwhile, overexpression of CHRNB2 significantly weakened the migration and invasion ability of pancreatic cancer with or without ACh (300 μM)." (PMID 36344976, 2022). "CHRNB2 could inhibit β-catenin pathway, EMT, migration and invasion of pancreatic cancer cells via ACh-independent mechanism." (PMID 36344976, 2022). "Our results showed that downregulation of CHRNB2 significantly increased the migration and invasion ability of pancreatic cancer with or without ACh (300 μM)." (PMID 36344976, 2022). "The role of CHRNB2 in pancreatic cancer progression was not investigated before." (PMID 36344976, 2022). "However, our results indicate that CHRNB2 could repress EMT and metastasis in pancreatic cancer, which emphasized distinct molecular regulation among different cancer types." (PMID 36344976, 2022). "However, our results showed that CHRNB2 could repress the EMT of pancreatic cancer without ACh, suggesting CHRNB2 has ACh-independent functions." (PMID 36344976, 2022).
prostate carcinoma (1 paper, 2022). A carcinoma that arises from epithelial cells of the prostate gland. "HLA-DRB5 was highly related to MHC-II genes, which were the related genes of prostate cancer, and so was the CHRNB2." (PMID 36376815, 2022).
schizophrenia (1 paper, 2022). A major psychotic disorder characterized by abnormalities in the perception or expression of reality. "In this way, we linked the gain for CHRNB2, a gene encoding an acetylcholine receptor subunit, to a cluster of regulatory elements situated in a schizophrenia-associated locus ~330kb downstream of the transcription-start site of the gene." (PMID 35316269, 2022). "For instance, using brain regulatory-interactions for augmentation, we were able to implicate two acetylcholine receptor subunits involved in post-synaptic chemical transmission, namely CHRNB2 and CHRNE, in schizophrenia." (PMID 35316269, 2022).
self-limited familial infantile epilepsy (1 paper, 2024). This syndrome is characterized by the onset of seizures between 3 and 20 months of age (peak 6 months). "In particular, several mutations were found in CHRNA4 and CHRNB2, whereas only four variants were reported in CHRNA2, including one in a family with self-limited familial infantile epilepsy (SeLFIE), previously known as benign familial infantile seizures (BFISs)." (PMID 39596607, 2024).
Stroke (1 paper, 2025). Sudden impairment of blood flow to a part of the brain due to occlusion or rupture of an artery to the brain. "Upregulation of ADGRL1, CDK5R1/CDKL3, CHRNB2, and ROR2 genes in post-stroke long-lasting brain fatigue generally supports neuroplasticity, cognitive recovery, and neurogenesis, which are beneficial for rehabilitation." (PMID 40006074, 2025). "The upregulation of ADGRL1, CDK5R1/CDKL3, CHRNB2, and ROR2 gene expression in the context of long-lasting post-stroke brain fatigue can have a mix of positive and negative effects, depending on how these proteins influence brain function, recovery, and energy regulation." (PMID 40006074, 2025).
tumor (5 papers, 2019 to 2025). "This suggests that not only tumor factors that worsen over time, but also the malignant potential acquired by the tumor itself, namely high CHRNB2 expression, are important for the formation of peritoneal dissemination." (PMID 40805184, 2025). "CHRNB2 knockdown significantly inhibited proliferation, migration, and invasion in vitro and suppressed tumor growth in vivo." (PMID 40805184, 2025). "Multivariate analysis identified high CHRNB2 expression and T4 tumor depth as independent predictors of peritoneal recurrence." (PMID 40805184, 2025). "On multivariable analysis, tumor depth (T4) (p < 0.0041, HR 5.69, 95% CI 1.95–16.6) and high CHRNB2 (p = 0.0417, HR 2.83, 95% CI 1.03–16.6) were independent prognostic factors for peritoneal recurrence." (PMID 40805184, 2025). "In particular, the expression of the CHRM1, CHRNA2, CHRNA4, CHRNA6, CHRNA7, and CHRNB2 genes was increased in samples from the tissue of the anterior edge of the tumor." (PMID 38393158, 2024). "In univariable analysis, tumor size (≥40 mm) (p = 0.0293, HR 4.03, 95% CI 1.15–14.2), high CEA (p = 0.0167, HR 3.44, 95% CI 1.25–9.49), tumor depth (T4) (p < 0.0001, HR 9.27, 95% CI 3.36–25.6), and high CHRNB2 (p = 0.0173, HR 3.29, 95% CI 1.23–8.79) were prognostic factors for peritoneal recurrence." (PMID 40805184, 2025). "Third, CHRNB2 expression in the primary tumor may also be used as a companion diagnosis when selecting anti-CHRNB2 antibody therapy in the future." (PMID 40805184, 2025). "Nicotine exposure alone and cisplatin treatment alone appeared to increase the mRNAs of CHRNA4, CHRNB2, and CHRNA3 in the tumor samples, while their combination resulted in further increases." (PMID 35565402, 2022). "The levels of mRNAs of CHRNA4, CHRNB2, and CHRNA3 in the tumor tissues were also quantified." (PMID 35565402, 2022). "Interestingly, while CHRNB2 KD cells exhibited partial tumor growth in proliferation and subcutaneous tumor models, they failed to form peritoneal metastases in a dissemination model." (PMID 40805184, 2025). "While the expression of many AChRs was not altered in comparison to the cellular tumor, we did find significant upregulations in the expression of CHRNA7, CHRNB2, CHRM1, and CHRM3 in these areas." (PMID 31590360, 2019).
cancer (4 papers, 2022 to 2025). A tumor composed of atypical neoplastic, often pleomorphic cells that invade other tissues. "As a mechanism by which CHRNB2 inhibits the metastasis of CRC, CHRNB2 has been reported to mediate cell survival, resistance to anticancer drugs, and stemness of cancer cells by inhibiting the activity of components of the PI3K–AKT and JAK–STAT signaling pathways." (PMID 40805184, 2025). "In previous studies, there are few studies on the relationship between CHRNB2 and cancer." (PMID 36344976, 2022).
CHRNB2 also shares sentences with these, for which no sentence is quoted: adenocarcinoma (2 papers); neurologic disorders (2); Alzheimer disease (1); Arthritis (1); arthropathy (1); autism (1); Basal ganglia calcification (1); breast carcinoma (1); channelopathy (1); COVID-19 (1); diabetes (1); Epileptic encephalopathy (1); Huntington disease (1); neurodegenerative disease (1); nocturnal frontal lobe epilepsy (1); psoriasis (1); retinitis pigmentosa (1); sleep disorder (1).